NOTCH1 (notch receptor 1)
Diseases named in the same sentence as NOTCH1 in open-access papers (continued):
Sharing a sentence is not in itself a finding about the gene and the disease.
endometrial cancer (31 papers, 2010 to 2025). Primary or metastatic malignant neoplasm involving the endometrium (mucous membrane that lines the endometrial cavity). "MiR-34a inhibited the proliferation, migration, invasion, EMT-associated phenotypes by downregulating Notch1 in endometrial cancer cells." (PMID 29340051, 2017). "Disruption of NOTCH1 signaling has been linked to complications such as preeclampsia, intrauterine growth restriction, polycystic ovary syndrome, endometriosis, adenomyosis, infertility, and endometrial cancer." (PMID 40625359, 2025). "The miR-34 molecule—and especially its miR-34b subtype—is strongly associated with the proliferation and invasion of endometrial cancer cells, while the miR-34a subtype inhibits proliferation, migration, and invasion by targeting Notch1 (Notch receptor 1) in cells of this type of tumor." (PMID 35628566, 2022). "Wnt/β-catenin, Hedghog, and Notch1 are the most frequently activated pathways in endometrial cancer stem cells." (PMID 38539419, 2024). "Notch1 is tumor-suppressive in human endometrial cancer cells, which ranked 11th in DriverRWH, while 61th in MutsigCV, 94th in Subdyquency, even 2630th in OncodriveFML and 7054th in Gravity." (PMID 35831792, 2022). "It is demonstrated that NIFK-AS1 increases the expression of Notch1 by interacting with miR-146a in endometrial cancer, and FGD5-AS1 affects periodontitis by regulating the FGD5-AS1/miR-142-3p/SOCS6 axis." (PMID 33936172, 2021). "In our study, we determined that NOTCH1 differentiates the samples obtained from endometrial cancer patients compared to the control group, including a decrease in the expression of the discussed gene being noted, which codes the NOTCH1 protein." (PMID 33917330, 2021). "On the other hand, AR was required for FOXA1-enhanced Notch pathway activation in endometrial cancer cells, increasing Notch1 and HES1 expression." (PMID 33167316, 2020). "Notch1 was found to be overexpressed in endometrial cancer tissues compared to normal endometrial tissues." (PMID 29340051, 2017). "Taken together, our results suggest that miR-34a plays tumor-suppressive roles in endometrial cancer through downregulating Notch1." (PMID 29340051, 2017). "Our current results reveal that miR-34a is significantly downregulated in endometrial cancer tissues and negatively correlated with Notch1 expression." (PMID 29340051, 2017). "It was reported that Msi1 modulated cell cycle progression and apoptosis via Notch-1 and p21 in endometrial carcinoma, and Msi1 modulated mammary progenitor cell expansion through the activation of the Wnt and Notch pathways." (PMID 25362645, 2014). "Certain signaling pathways were differentially targeted by miR-146a-5p in various cancers, including LIF-Stat3 when reported in the endometrium of patients with implantation failure, NOTCH 1/2 in endometrial carcinoma, and the EGFR, NF-κB, TGF-β, and SMAD4 pathways in other tumor types." (PMID 37240034, 2023). "Through the NF-B/Notch1 signaling pathway, visfatin drives malignant behavior in the development of endometrial cancer and may stimulate cell proliferation, among other things." (PMID 36072980, 2022). "Similarly, the reduction of lncRNA NIFK-AS1 in TAM of endometrial cancer leads to miR-146a-mediated suppression of Notch1 signaling, which promotes M2-like macrophage-driven proliferation, migration, and invasion of cancer cells." (PMID 36263199, 2022). "It is highly expressed in endometrial cancer and can regulate the endometrial cancer cell cycle and cell apoptosis by interacting with the stem cell-related factor Notch-1 and its downstream targets (transcription factor Hes-1 and cell cycle regulator WAF1/CIP1)." (PMID 33747079, 2021). "However, on the proteome level, these researchers, using the Western blot method, observed the lack of a significant difference in the concentration of the NOTCH1 protein in the samples obtained from endometrial cancer patients compared to the control." (PMID 33917330, 2021).
endometrial cancer (continued). "In addition, lncRNA DCST1-AS1 was increased in endometrial carcinoma via sponging miR-92a-3p and inducing Notch1." (PMID 34414241, 2021). "Importantly, further results suggested miR-34a was significantly downregulated in endometrial cancer tissues and negatively correlated with Notch1 expression." (PMID 29340051, 2017). "Furthermore, we verified that miR-34a acts as a tumor suppressor by downregulating Notch1 in endometrial cancer." (PMID 29340051, 2017). "To verify whether mir-34a is a regulator of NOTCH1 and DLL1 in human endometrial cancer cells, we designed experiments of gain- and loss-of-function of mir-34a in the Ishikawa cell line." (PMID 27039384, 2016). "To note, notch-1, and its modulator MSI1 are expressed in the human endometrium, and have been linked to a putative dysregulation of endometrial stem cell function in endometriosis and endometrial carcinoma." (PMID 20585575, 2010). "In the final stage, the expression changes of TGFβ1, NOTCH1, and BCL2L on the protein level were assessed within G1–G3 endometrial cancer specimens in comparison to the control." (PMID 33917330, 2021). "Another report indicated that overexpression of BHLHE41 in endometrial cancer Ishikawa and HEC-1B cells inhibited cell migration, invasion, and metastasis by attenuating NOTCH1 signaling." (PMID 31487856, 2019). "Attenuating Notch1 signaling mediated the suppressive effect of enhancer-of-split and hairy-related protein 1 on EMT and metastasis in endometrial cancer." (PMID 26563263, 2015). "Given that TCGA database analyses for this study identified Notch-1 as a negative prognostic marker in endometrial carcinoma (p = 0.004), we tried to characterize the relationship between Msi-1 and Notch-1." (PMID 35619161, 2022).
Stroke (26 papers, 2012 to 2025). Sudden impairment of blood flow to a part of the brain due to occlusion or rupture of an artery to the brain. "Taken together, these results suggest that LIPUS promotes the differentiation of OPCs and improves the integrity of cerebral WM after stroke mainly through IL-17A/Notch1 signaling." (PMID 40290135, 2025). "Neurogenesis plays an important role in the prognosis of stroke patients and is known to be promoted by the activation of the Notch1 signaling pathway." (PMID 36009031, 2022). "We also found that LRIC modulated miR-449b/Notch1 to promote neurological function recovery during the chronic phase of stroke." (PMID 36009031, 2022). "We previously reported that folic acid supplementation stimulated neural stem cell proliferation by Notch signalling after rat experimental stroke;49 however, this study showed that FD enhanced Notch1 expression in activated microglia." (PMID 31087489, 2019). "Although Notch1 has been shown to worsen stroke outcome through glial cell-mediated inflammatory responses, the molecular mechanisms of γ-secretase dependent association of Notch1 processing with hazardous outcomes of cigarette smoke exposure remain elusive." (PMID 30794693, 2019). "In this study, firstly, we aimed to detect the temporal evolution of Notch1 signaling activation and NSCs responses after stroke." (PMID 30131677, 2018). "In this study, we first investigated the temporal evolution of Notch1 signaling at the early stage of stroke." (PMID 30131677, 2018). "With this study, we provided additional evidence that the adult brain can undergo neural replacement from endogenous precursors to repair itself after stroke, which was shown here to be controlled by the activity of Notch1 signaling." (PMID 30131677, 2018). "At 4 weeks, compared with the stroke group, the expression of Notch1 and Hes1 mRNA transcripts in the PSD group decreased, and again increased after treatment with FXT or YNJYP." (PMID 30386260, 2018). "Studies have shown that astrocytes can promote angiogenesis via VEGF and Notch 1 signalling and neurovascular remodelling and recovery after stroke, whereas microglia can produce angiogenic factors and promote angiogenesis after stroke." (PMID 30315331, 2018). "At 4 weeks, compared with the stroke group, the expression of Notch receptor Notch1 mRNA transcripts in the PSD group decreased, but also increased after treatment with YNJYP." (PMID 30386260, 2018). "At 4 weeks, the expression of Notch1 mRNA transcripts for rats in the PSD group was lower than that for rats in the stroke group (P < 0.01), but significantly increased after treatment with FXT or YNJYP (P < 0.01)." (PMID 30386260, 2018). "It is relevant therefore to note that proliferating reactive astrocytes are regulated by Notch-1 in the peri-infarct area after stroke." (PMID 26608466, 2015). "Notch1 signaling was reduced in striatal astrocytes after stroke while ectopic activation in astrocytes inhibited stroke-induced neuroblast production." (PMID 26136658, 2015). "In conclusion, LIPUS improves long-term functional recovery by ameliorating the inflammatory state after stroke and inhibiting IL-17A/Notch1 signaling to promote WM repair, which provides a promising novel therapeutic approach for stroke and other demyelinating diseases." (PMID 40290135, 2025). "A recent study also revealed that Presenilin 1-based Notch 1 signaling may control the generation, proliferation, and self-renewal of Rad-PCs isolated from the cortical peri-infarct areas after stroke." (PMID 37082656, 2023). "A previous study revealed that reactive astrocytes could express NICD1 and could also be regulated by Notch1 after stroke." (PMID 34646085, 2021).
Stroke (continued). "The SanBio study assessed the use of SB623 cells, which are allogenic modified BMSCs transiently transfected with the human Notch-1 intracellular domain, in a two-year, single-arm, open-label, uncontrolled study of 18 patients in a stable chronic phase after stroke (6–60 months post-stroke)." (PMID 32937754, 2020). "In recent years, Notch1 signaling, which is critical for endogenous neurogenesis, has been regarded as a potential therapeutic target for promoting functional recovery after stroke." (PMID 30131677, 2018). "Moreover, several studies have found that Notch-1 signaling was activated in the acute stage of stroke to promote NSCs proliferation and was attenuated in the subacute stage to promote neuronal differentiation." (PMID 30131677, 2018). "In our previous study, we demonstrated that Notch1 signaling could be blocked by DAPT at day 4 after stroke." (PMID 30131677, 2018). "Previous study have shown that Notch1 could regulate the proliferation of reactive astrocytes in the peri-infarct region after stroke." (PMID 29311941, 2017). "Notch1 has been reported as a key factor required for reactive astrocyte activation in the infarct region as well as worsening brain damage and functional outcome after stroke." (PMID 29311941, 2017). "Notch1 and its ligand Jagged1 have been implicated in post-ischaemic neovascularisation in both experimental and clinical stroke, where increases in the expression of activated Notch1 (Notch intracellular domain or NICD) in peri-infarct endothelial cells are coupled with the level of angiogenesis." (PMID 38247804, 2024). "To investigate whether Notch1 plays the role as a regulatory hub during the acute phase of cerebral ischemia–reperfusion injury and whether it affects neuronal pyroptosis after stroke, we examined the protein expression of Notch1 and NLRP3 in the ischemic penumbra of mice on day 3 after MCAO." (PMID 38137105, 2023). "However, it is unclear how miR-449b/Notch1 pathways are involved in stroke recovery." (PMID 36009031, 2022). "First, we evaluated the activity of Notch1 signaling at the acute and subacute phase of ischemia by histochemical analysis of the NICD from day 1 to day 7 after the induced stroke." (PMID 30131677, 2018). "Importantly, blocking Notch1 signaling activation at the appropriate time to expand neural progenitor pools and augment neural differentiation may be a therapeutic intervention with significant benefits to stroke patients." (PMID 30131677, 2018). "SB623 cells are derived from marrow stromal cells by transfection with a Notch1 intracellular domain (NICD)-expressing plasmid and are known to elicit functional improvement in experimental stroke." (PMID 23531336, 2013). "This aberrant EC activity is driven by sustained Notch1 signaling, and the increase in Notch1 signaling is triggered by an increase in the circulating Notch1 ligands DLL1 and Jagged1 in mice and humans after stroke." (PMID 40565303, 2025). "Our previous research highlighted an inconsistency with Notch1 signaling-related compensatory neurogenesis after chronic mild stress (CMS) in rodents suffering from cerebral ischemia, which continue to display post-stroke depressive symptoms." (PMID 22912748, 2012). "Background and Purpose: It is still not clear whether Notch1 signaling inhibition can promote functional outcomes after stroke, given that it plays time-dependent roles in the sequential process of endogenous neurogenesis." (PMID 30131677, 2018). "Notably, preventing Notch1 cleavage into the Notch intracellular domain (NICD) with the γ-secretase inhibitor N-[N-(3,5-diuorophenacetyl)-1-alanyl]-S-phenylglycine t-butylester (DAPT), subsequently improves functional outcomes following stroke." (PMID 30131677, 2018).
liver fibrosis (25 papers, 2012 to 2025). "SCLC-delivered POSTN signals communicate with fibroblasts, resulting in high NICD levels and liver fibrosis, reversible by NOTCH1 interference and γ-secretase inhibitor treatment." (PMID 39762921, 2025). "The interaction between Jagged-1 on liver macrophages and Notch1 on HSCs drives Notch1-mediated HSCs activation and liver fibrosis." (PMID 40977736, 2025). "Utilising similar antibodies targeting IGF2BP3, Jag1, Notch1/3, and Hes1 as a therapeutic strategy in pre‐existing liver fibrosis models would enhance the translational value of these discoveries." (PMID 39113232, 2024). "It has also been reported that CD44ICD in the nucleus binds to the CD44ICD response element on the NOTCH1 promoter region and initiates the transcription of Notch1, contributing to liver fibrosis." (PMID 38790021, 2024). "In liver fibrosis, TGFβ1 upregulates p-Smad2/3, Jagged1, Notch1 and Hes1, leading to trans-differentiation of hepatic stellate cells into myofibroblast cells." (PMID 32724452, 2020). "Inhibition of the Notch1 signalling pathway with DAPT also prevents cholestatic liver fibrosis by decreasing the differentiation of hepatic progenitor cells into cholangiocytes." (PMID 31718671, 2019). "Notch1 signalling is implicated in hepatic fibrogenesis and DAPT treatment has a protective effect on hepatocytes and ameliorates liver fibrosis." (PMID 31718671, 2019). "Here, we provided evidence that quercetin inhibited liver fibrosis through regulating macrophage polarization and function via Notch1 pathway." (PMID 29497376, 2018). "Both protein and gene expression of Notch receptors (Notch-1 and -3) were significantly upregulated after 8 weeks of liver fibrosis." (PMID 26658360, 2015). "We further hypothesized that forced activation of Notch1 in αSMACre+/NICD1 mice will aggravate liver fibrosis." (PMID 39529885, 2024). "In a murine model of liver fibrosis infected with Schistosoma japonicum (a parasite that is endemic in Asia), inhibition of the Notch1/Jagged1 signaling pathway could reverse macrophage M2 polarization, thereby alleviating liver fibrosis." (PMID 37849830, 2023). "HAS2 mediated hyaluronan production through Notch1 activation and liver fibrosis." (PMID 33506044, 2021). "Although the expression of Notch1 and Notch4 decreased during the progression of hepatic fibrosis, the expression pattern of Hes1, a target gene downstream of Notch signaling, was similar to Notch3 and Jagged1, fluctuated with the progression and regression of hepatic fibrosis." (PMID 34239344, 2021). "In addition, Notch1 is involved in the mesenchymal program by activating Snail expression in liver fibrosis development." (PMID 23226767, 2012). "Furthermore, the effects of inhibitory antibodies against NOTCH1 or NOTCH2 might be effective in other models of liver fibrosis." (PMID 39529885, 2024). "In addition, in mouse models of liver fibrosis infected with Schistosoma japonicum, inhibition of Notch1/Jagged1 signaling pathway could reverse the M2 polarization of macrophages, thereby alleviating liver fibrosis." (PMID 35990625, 2022). "Thus, results obtained from patient samples and our in vitro analysis using hepatocytes indicate that upregulation of NOTCH1 resulting from downregulation of miRNA-449a stabilizes nuclear P65 to activate YKL40 expression in patients with HCV mediated hepatic fibrosis." (PMID 23226395, 2012). "It has been reported that Notch1 signal transduction is a downstream effector pathway of SIRT1, which can affect the progression of liver fibrosis, acute lung injury, and osteoporosis." (PMID 41333237, 2025). "Notch1 signaling has been stated as a downstream effector pathway of SIRT1 to affect disorder progressions, such as liver fibrosis." (PMID 37934372, 2023). "Notch1 is known to regulate Snail and Slug mRNA levels, but efforts have not been made to examine alternative functions of NICD and Snail expression in liver fibrosis." (PMID 23226767, 2012).
liver fibrosis (continued). "In addition to genetic manipulation, we investigated the effect of antibodies against NOTCH1 and NOTCH2 on the development of liver fibrosis." (PMID 39529885, 2024). "In addition to genetic manipulation, we have investigated the effect of antibodies against NOTCH1 and NOTCH2 on the development of liver fibrosis." (PMID 39529885, 2024). "We also found that Notch1/HES1 may be involved in sodium arsenite exposure-induced liver fibrosis and autophagy, and PTEN can regulate Notch1/HES1 to affect autophagy and fibrosis." (PMID 37505544, 2023). "Additionally, the downregulation of NOTCH1 and CREB genes was observed, although their exact roles in mitigating liver fibrosis are ambiguous." (PMID 37893992, 2023). "Studies have shown that the Notch1 and TGFß/BMP signalling pathways can regulate gene expression of Hesl and thus induce HSC activation, suggesting that Notch signalling pathways regulate the activation of HSCs involved in the progression of liver fibrosis." (PMID 33446761, 2021). "However, treatment with either anti-NOTCH1 or anti-NOTCH2 antibodies did not change the degree of liver fibrosis in either CCl4 or in DDC-model." (PMID 39529885, 2024). "The levels of expression of Notch1-ICD and Notch2-ICD proteins did not change significantly during liver fibrosis, as indicated by Western blot analysis." (PMID 23056328, 2012).